CD4 (CD4 molecule)
Diseases named in the same sentence as CD4 in open-access papers (continued):
Sharing a sentence is not in itself a finding about the gene and the disease.
AIDS (continued). "By contrast, group B (subjects with a relatively high baseline CD4 count (≥453 cells/mm3) and low steady-state viral load (<17,500 copies/ml)) was associated with a 15% reduced probability of developing AIDS in the future." (PMID 18776933, 2008). "In support of a role for X4 viruses in disease progression, studies with macaques infected with SIV carrying CXCR4-tropic HIV-1 envelope (SHIV chimera) display rapid loss of CD4 counts and develop AIDS faster than the R5 counterpart." (PMID 17651505, 2007). "The ability to directly lyse CD4+ T cells have been postulated to at least partially cause the reduction of these immune effecter cells which leads to the clinical condition of AIDS." (PMID 17945027, 2007). "It is seen that the average decrease in CD4 T-cell count over the first ten years induces a much stronger increase in AIDS risk than does the average increase in viral load." (PMID 17888148, 2007). "This provides, at least in part, a plausible explanation contributing to CD4+ T-cell depletion that occurs in HIV-1-infected individuals who progress to AIDS whilst exclusively harbouring R5 HIV-1 variants." (PMID 18076768, 2007). "Since the effect of changes in CD4 count on AIDS risk is much larger at low counts than at high counts, changes at high counts give smaller changes in the graph." (PMID 17888148, 2007). "This allele carries Arg instead of His at position 186 (186R) and is strongly associated with faster decline of CD4 T cells and accelerated progression to AIDS." (PMID 17651505, 2007). "A large Swiss study showed HCV serum-positivity was associated with more likely progression to AIDS and a less likely increase of CD4+ cell count after therapy." (PMID 17958914, 2007). "When evaluated on the logarithmic relative AIDS risk scale, the RNA slope changes from 0.167 × 1.422 = 0.24 to 0.223 × 1.422 = 0.32, whereas the CD4 slope changes from 0.43 × 0.5801 = 0.25 to 1.27 × 0.5801 = 0.74." (PMID 17888148, 2007). "Although shapes were similar, the average decline in CD4 count corresponded to a much larger change in AIDS risk than the average increase in viral load did." (PMID 17888148, 2007). "CCR5-restricted (R5) human immunodeficiency virus type 1 (HIV-1) variants cause CD4+ T-cell loss in the majority of individuals who progress to AIDS, but mechanisms underlying the pathogenicity of R5 strains are poorly understood." (PMID 18076768, 2007). "Note that also in the current analysis average HIV RNA level six months after seroconversion was more clearly associated with time to AIDS than CD4 T-cell count was." (PMID 17888148, 2007). "The effects of time-updated marker values on AIDS risk are used to directly compare average patterns of CD4 T-cell count and HIV RNA level on a common scale." (PMID 17888148, 2007). "In biomedicine, the identification of specific genetic variants responsible for an HIV patient's time-dependent CD4 count and for the time to onset of AIDS symptoms can help to design individualized drugs to control this patient's progression to AIDS." (PMID 16539724, 2006). "HAART is effective in increasing CD4 cell counts and in decreasing the virus load, so it has been associated with a 50% decrease in morbidity and mortality with AIDS." (PMID 17087819, 2006). "Signaling via the IL7R is essential for T cell homeostasis and maintenance of T cell memory, and down-regulation of IL7R correlates with depletion of CD4+ T cells and AIDS (acquired immune deficiency syndrome) progression." (PMID 17014716, 2006). "We examined trends in SIR with respect to time relative to AIDS onset and CD4 count, as measures of immune deficiency." (PMID 16868538, 2006). "Breast cancer risk varied little by CD4 count (Ptrend=0.47) or AIDS-relative time (Ptrend=0.14) or after adjustment for established cancer risk factors." (PMID 16868538, 2006).
AIDS (continued). "We believe that the surprising power of the absolute lymphocyte count in predicting the time to an AIDS-related event stems both from the lymphopenia seen in malnutrition associated with advanced AIDS as well as the depletion of the CD4 positive population." (PMID 16916461, 2006). "Those who have a pre-treatment CD4 cell count < 200/mm3 or have insufficient CD4 cell responses to HAART are at risk for progressing to AIDS or dying while receiving therapy." (PMID 16262894, 2005). "In this analysis of TB cases in a cohort of adults living with HIV in the Asia-Pacific, we found that low CD4+ cell counts (<200 cells/μL) and low total serum cholesterol (≤3.9 mmol/L), adjusted for sex, BMI, prior AIDS, and HIV viral load were associated with greater odds of TB diagnosis." (PMID 40965078, 2026). "The progressive loss of CD4+ T-lymphocytes and the role of these cells in coordinating immune response explain the severe immune impairments, leading to acquired immunodeficiency syndrome (AIDS)." (PMID 41425555, 2025). "HIV primarily infects CD4+ T cells, leading to their depletion and progression to acquired immunodeficiency syndrome (AIDS)." (PMID 40006751, 2025). "Infection with human immunodeficiency virus (HIV), the virus species that leads to acquired immunodeficiency syndrome (AIDS), causes selective loss of CD4+ T cells, permanently reshaping the immune system." (PMID 41294846, 2025). "Over 30% of PWH who initiate cART with low CD4 counts experience poor CD4 T cell reconstitution, with greater immune hyper-activation and inflammation compared to those with better CD4 recovery, and at an elevated risk for comorbidities and non-AIDS events." (PMID 40779581, 2025). "Notably, seborrheic dermatitis has been significantly associated with marked reduction in CD4-positive T cell counts (<200/mm3), and is considered a potential clinical marker of advanced AIDS." (PMID 41035583, 2025). "A number of CD4 + T cells below 200/μL is a risk factor for severe infection, while 50/μL is a risk factor for CMV reactivation in acquired immunodeficiency syndrome." (PMID 40526215, 2025). "In addition, three SNPs (IL1B rs1143623, STAT1 rs1467199 and STAT1 rs2066804) were associated with CD4+ T cell counts in patients with AIDS." (PMID 40331958, 2025). "HIV infection drives the progressive depletion of CD4+ T lymphocytes, resulting in an immunocompromised state that predisposes to opportunistic infections with accelerated progression to advanced disease states, including AIDS-defining malignancies." (PMID 40559542, 2025). "Human immunodeficiency virus (HIV) is a retrovirus that targets the immune system, primarily attacking and depleting CD4+ T cells, resulting in the progressive collapse of immune function and the development of acquired immunodeficiency syndrome (AIDS)." (PMID 40316910, 2025). "CD4 cell count is closely associated with the survival rate of patients with AIDS." (PMID 40456121, 2025). "The introduction of HAART has significantly impacted the virus's replicative capacity, leading to notable benefits such as increased CD4 counts and reduced progression to full‐blown Acquired Immunodeficiency Syndrome (AIDS)." (PMID 40176606, 2025). "Human immunodeficiency virus type 1 (HIV-1) is an enveloped retrovirus that primarily infects CD4+ T cells, macrophages, and dendritic cells, leading to progressive immune suppression and, if untreated, acquired immunodeficiency syndrome (AIDS)." (PMID 40733528, 2025). "HIV is the etiological agent of acquired immunodeficiency syndrome (AIDS), a severe disease that affects the immune system, primarily CD4+ T-helper cells, thereby rendering the body susceptible to infections." (PMID 40650152, 2025). "This ratio can be affected by coinfection or inflammation, as shown in a study where patients with hepatitis C virus coinfection and cardiovascular disease exhibit lower CD4/CD8 ratios, associated with the duration of the HIV infection, nadir CD4+ cell count, and AIDS." (PMID 40969513, 2025).
AIDS (continued). "While immunocompromised individuals (e.g., HIV/AIDS patients with CD4 counts <100 cells/μL) are at highest risk, immunocompetent hosts may also develop progressive infections, particularly in the central nervous system." (PMID 41541964, 2025). "A progressive decline in CD4+ T cell count is a hallmark of untreated HIV infection and is a key factor in the progression to acquired immunodeficiency syndrome (AIDS)." (PMID 40432125, 2025). "The human immunodeficiency virus (HIV) compromises the immune system by damaging CD4+ T lymphocytes and, if untreated, leads to acquired immunodeficiency syndrome (AIDS)." (PMID 40244151, 2025). "Since the majority of E. africanus cases are diagnosed in patients with advanced HIV disease (AIDS) and thus very low CD4+ T-lymphocyte counts, a Rag-1-deficient (devoid of mature T and B lymphocytes) murine model of infection was established to study the infection in an immunocompromised host." (PMID 38198478, 2024). "Human immunodeficiency virus (HIV) is a retrovirus that attacks the cells within the immune system, predominantly the CD4+ cells, and culminates in Acquired Immunodeficiency Syndrome (AIDS)." (PMID 38792830, 2024). "In this article, we present a mathematical model for human immunodeficiency virus (HIV)/Acquired immune deficiency syndrome (AIDS), taking into account the number of CD4+T cells and antiretroviral treatment." (PMID 38665242, 2024). "In patients with Acquired Immune Deficiency Syndrome (AIDS) having an active SARS-CoV-2 infection, CD4+ T-cell lymphopenia is associated with poorer outcomes, even when nAbs are produced." (PMID 39460293, 2024). "Human immunodeficiency virus (HIV), especially HIV-1, is the causative agent of acquired immune deficiency syndrome (AIDS), which attacks CD4+ T cells and damages the immune system." (PMID 38435698, 2024). "However, in this study marker of CD4+ T cell exhaustion had an association with the non-AIDS defining events that became insignificant after adjusting for CD4+ T cell count." (PMID 38914935, 2024). "This could lead to an increased risk of HIV-associated non-AIDS complications and the dysfunction of T cells, despite long-term viral suppression by cART and restoration of CD4+ T cell levels." (PMID 38400063, 2024). "The results showed that low CD4 was associated with higher AIDS-related mortality." (PMID 39058196, 2024). "Without treatment, human immunodeficiency virus type I (HIV-1) infection leads to gradual decrease of CD4+ T cells and to acquired immunodeficiency syndrome (AIDS) in most patients." (PMID 38426331, 2024). "Also, there is higher CXCR4 expression in HIV as CXCR-4 also serves as a co-receptor for HIV entry into CD4+ cells and is associated with more rapid immunosuppression and faster progression to AIDS." (PMID 39001265, 2024). "Notably, CD4 T-cell levels in GBM patients approach the nadir observed in individuals with acquired immune deficiency syndrome (AIDS), underscoring the severity of the immune suppression." (PMID 38727262, 2024). "These early studies pointed out or confirmed that the CD4+ T cell was a major target of the new disease eventually called AIDS and that loss of CD4+ T cells or their function could begin to explain AIDS-related opportunistic infections and malignancies." (PMID 38949029, 2024). "This is the case of Alzheimer's disease (AD), in which Aβ and Tau work as Eg5 inhibitors, or in acquired immune deficiency syndrome (AIDS), in which Tat-mediated Eg5 determines the loss of CD4+ T-lymphocytes." (PMID 38939361, 2024). "It targets CD4+ lymphocytes, integrating into the host–cell genome, and leads to acquired immunodeficiency syndrome (AIDS)." (PMID 39066420, 2024). "A retrospective study conducted in France from 1996 to 2013 found that a significant proportion of PEL patients had experienced severe immune deficiency, with 65% having a prior history of AIDS-defining conditions, and 25% still exhibiting CD4 counts below 200 cells/μL at PEL diagnosis." (PMID 39749085, 2024).
AIDS (continued). "Ultimately, as CCR5+ CD4+ T cells are extensively destroyed, HIV proliferates, aggregates, and spreads, resulting in severe immune system deficiency, which progresses to Acquired Immune Deficiency Syndrome (AIDS)." (PMID 39519859, 2024). "Infection with HIV/AIDS has been linked to an increased risk of developing cataracts and a higher likelihood of requiring cataract surgery, particularly in individuals with low CD4 cell counts." (PMID 39588421, 2024). "However, a considerable proportion of PLHIV fail to improve their CD4 + T cell level despite of successful viral suppression, who have an increased risk of developing AIDS-related and non-AIDS-related events, and death." (PMID 38287246, 2024). "In animals treated with a cell-depleting CD8α antibody at the time of infection, stHIV-A19 maintains chronically elevated plasma viral loads with progressive CD4+ T-cell loss and the development of acquired immune-deficiency syndrome (AIDS)-defining clinical endpoints." (PMID 39459950, 2024). "BA was first described in patients with acquired immunodeficiency syndrome (AIDS) with very low CD4 cell counts." (PMID 39229389, 2024). "We implemented an exploratory panel of 35 circulating co-stimulatory and inhibitory checkpoint proteins and their association with poor CD4 T-cell reconstitution among participants enrolled in the AIDS Clinical Trials Group Longitudinal Linked Randomized Trials cohort." (PMID 39287441, 2024). "The risk of AIDS-related mortality was higher among PLWH with CD4 < 200 cells/μL (1.53 [1.16–2.02]), those with a history of an AIDS-defining illness (4.22 [3.35–5.32]), and those with 2 comorbidities (1.38 [1.02–1.98]) compared with those without comorbidities." (PMID 38560603, 2024). "Higher viral load often corresponds to accelerated depletion of CD4 cells and advancement to acquired immunodeficiency syndrome (AIDS)." (PMID 38845923, 2024). "This study, published in the Journal of Acquired Immune Deficiency Syndromes, explores the relationship between CD4/CD8 ratios and CD4 counts in PWH in Uganda." (PMID 38428854, 2024). "Initially, it was hypothesized that low CD4 counts associated with AIDS or HIV would result in poor cancer responses, viral reactivation, or increased toxicity from immunotherapy, leading to the exclusion of these patients from early clinical trials." (PMID 39807457, 2024). "AIDS-associated KS occurs mostly in patients with low-CD4+ counts, so the impairment of CD4+ lymphocytes induced by JAK inhibitors could be another explanation for iatrogenic KS." (PMID 37693927, 2023). "Low CD4 count and high viral load increase the risk of progression to AIDS among COVID-19 patients." (PMID 37288215, 2023). "A reduction in CD4-cell count below 200 cells/mm3 of blood, known as AIDS, can therefore cause severe immunocompromise of the host, leaving the host vulnerable to opportunistic infections such as esophageal candidiasis, Pneumocystis jirovecii pneumonia, or cytomegalovirus retinitis." (PMID 37303361, 2023). "Meanwhile, prior research on Human Immunodeficiency Virus/Acquired Immune Deficiency Syndrome (HIV/AIDS) patients identified a significant relationship between ALC and CD4 cell count with an r-value of 0.327 (p < 0.05) (Agrawal, Rane & Jadhav, 2016)." (PMID 37377785, 2023). "It is also vital to investigate the risk factors involved in these situations, such as advanced age, previous diagnosis of AIDS, low CD4+T cell count, viral co-infections, and risk behaviors common to people living with HIV, such as smoking and alcohol consumption." (PMID 37341221, 2023). "Acquired immune deficiency syndrome (AIDS) is a pathology caused by the human immunodeficiency virus (HIV) capable of weakening the immune system, mainly by affecting the CD4+ T lymphocytic cells." (PMID 36226448, 2023).
AIDS (continued). "Within this cohort, we recently reported that the risk of severe COVID-19 outcomes was increased in individuals with uncontrolled HIV replication, low CD4+ cell count and prior AIDS, independently of general risk factors such as age, comorbidity burden, and non-Western origin (F.W.N.M." (PMID 37395254, 2023). "Interestingly, AIDS events have been described in a few ECs with loss of CD4+ T cells, despite maintaining undetectable viral loads." (PMID 36672667, 2023). "Chronic T cell activation and inflammation are the best independent predictors of progression to AIDS, better than plasma viral loads (pVLs) or CD4+ T cell counts, being closely associated with non-AIDS-associated comorbidities and mortality in both HIV and SIV infections, even on ART." (PMID 37485874, 2023). "Since CD4+ T lymphocytes are the regulators of the adaptive immune system, their depletion effectively weakens the immune system, leading to the acquired immune deficiency syndrome (AIDS) stage of the infection." (PMID 37408185, 2023). "Low CD4+T cell count, OIs, were all associated with death of individuals with AIDS-related PML." (PMID 38029233, 2023). "However, it is also possible that the sole presence of those cells in AGMs is sufficient to compensate the loss of CD4+ T-cells by ensuring part of their immunological functions, thus contributing to the protection of AGMs against AIDS." (PMID 36813761, 2023). "Higher BMI (OR 0.57, p<0.001) and higher current CD4+ T-cell count (OR 0.99, p<0.5) were also significantly associated with reduced sarcopenia risk, and history of AIDS (OR 10.71, p<0.01) and protease inhibitor (PI) exposure (OR 3.53, p<0.01) were associated with increased sarcopenia risk." (PMID 37594923, 2023). "outbreaks demonstrated an increased risk of death associated with advanced AIDS (CD4 counts <75 mm3), immunocompromised states (such as solid organ transplantation), chronic renal disease, and prolonged use of corticosteroids or tumor necrosis factor (TNF) antagonists." (PMID 36602962, 2023). "During HIV infection, direct cell destruction because of HIV infection and the proliferation and destruction of infected cells by HIV antigen-specific CD8+ cytotoxic T-cells (CTLs) decreases the CD4+ T-cell count and consequently causes acquired immunodeficiency syndrome (AIDS)." (PMID 37892225, 2023). "Diagnosis at younger age, with symptoms of acquired immunodeficiency syndrome (AIDS) or low CD4 counts (<200 cells/mm3) concomitant with missing physician or clinical appointments and reduced adherence to ART, all contribute to virological failure (VF)." (PMID 38140680, 2023). "Moreover, PLHIV who were diagnosed with the most advanced stage of HIV-1 (CD4 < 200 cells/mm3 and AIDS-defining conditions) were 2.75 times more at risk for VF compared to other patients." (PMID 38140680, 2023). "An additional 16 (24.2%) deaths with unknown cause were among participants who had AIDS according to immunologic criteria (most-recent CD4 < 200 cells/μL)." (PMID 37170118, 2023). "A future direction is to understand whether these altered immune profiles (low CD4/CD8 ratio or high CD8 count) protect against certain non-AIDS events, such as the risk of bacterial infections, as suggested in a previous study." (PMID 37639938, 2023). "Although these ratios provide good prognostic information on non-AIDS related events, limited research has been conducted to assess whether CD4:CD8 ratio are linked to any disease-specific burden." (PMID 36851599, 2023). "The literature reports that a low CD4 + T-cell count was a high-risk factor affecting the prognosis of patients with AIDS combined with CM, and the CD4 + T-lymphocyte count of the 32 patients in Group A was less than 100 cells/μl, accounting for 93.8%, which is consistent with clinical reports." (PMID 37024795, 2023).